MIR551B (microRNA 551b)
Synonyms: hsa-mir-551b; MIRN551B; mir-551b
Gene: MicroRNA gene on chromosome 3 (168,551,854 to 168,551,949, forward strand). Ensembl gene ENSG00000207717.
Gene Ontology:
Biological process: miRNA-mediated post-transcriptional gene silencing
Cellular component: RISC complex